ILK (integrin linked kinase)
Diseases named in the same sentence as ILK in open-access papers (continued):
Sharing a sentence is not in itself a finding about the gene and the disease.
cancer (continued). "The therapeutic/chemopreventative effects of aspirin in cancer are also mediated by direct inhibition of integrin-linked kinase (ILK) signaling and by decreased expression of c-Myc in cancer cells." (PMID 29246216, 2017). "Integrin-linked kinase (ILK) is a multifunctional adaptor protein which is involved with protein signalling within cells to modulate malignant (cancer) cell movement, cell cycle, metastasis and epithelial–mesenchymal transition (EMT)." (PMID 27576342, 2016). "ILK stabilises β1 adhesions, is associated with integrin engagement/activation and was found to be over-expressed in mesenchymal cancer cells." (PMID 25119572, 2014). "Integrin linked kinase (ILK) is a protein well established for its role in proliferation and cancer biology." (PMID 24911651, 2014). "Recently, ILK was reported to play an important role in centrosome clustering in cancer cell lines by modulating the microtubule associated proteins TACC3 and ch-TOG." (PMID 23825799, 2013). "Integrin-linked kinase (ILK) is a nodal molecule in many molecular pathways that are implicated in cancer metastasis." (PMID 22295247, 2012). "ILK also has an important role in cancer since it has oncogenic properties when overexpressed in cancer cell lines, and high ILK expression in a variety of malignancies is associated with a negative prognosis." (PMID 21806815, 2011). "Up-regulation of ILK in tumour cells is observed in several types of cancer, and is associated with tumour stage, metastasis and worse prognosis." (PMID 21426571, 2011). "Increased ILK expression and activity is found in association with many cancer types including: breast, brain, prostate, pancreatic, colon, gastric, ovarian, and malignant melanomas." (PMID 19409087, 2009). "As part of focal adhesion complexes, Integrin-Linked Kinase (ILK) was recently introduced as potent cancer target." (PMID 19649326, 2009). "ILK has been implicated in the development of various diseases, particularly cancer." (PMID 42185966, 2026). "ILK dysregulation is associated with a variety of human cancers." (PMID 40171447, 2025). "Furthermore, we examined a key developmental pathway linked to cancer stemness in OC spheroids, the Wnt pathway, and ILK inhibition markedly downregulated several pathway members, including Fzd7 and β-catenin target gene c-Myc at mRNA levels." (PMID 38822429, 2024). "Additionally, integrin-linked kinase (ILK)-mediated epithelial-mesenchymal transition (EMT) exerts great contribution to increase cancer cell adhesion and invasion." (PMID 37770930, 2023). "Overexpression of ILK is also implicated in pathophysiological conditions, including cancer." (PMID 38077324, 2023). "Previous studies confirmed that Postn is closely related to cancer progression and may promote tumor invasion through the ILK (Integrin-linked protein kinase)/RAC-alpha serine (AKT)/Serine/threonine-protein kinase mTOR (mTOR) pathway." (PMID 35676936, 2022). "ILK-expressing EVs derived from primary tumor are reported to promote EV uptake in the recipient cells which may further promote activation of cancer-associated signaling in the cells." (PMID 36505879, 2022). "However, the correlation among long non-coding RNA cancer susceptibility candidate 9, miR-542-3p and integrin-linked kinase in CRC is still unclear." (PMID 35427373, 2022). "The association of ILK with overexpression in many cancers has been reported." (PMID 35317111, 2021). "Several studies address how the extracellular matrix and integrin-mediated adhesion may trigger autophagy via FAK and ILK (integrin linked kinase), thus linking it to anoikis and cancer progression (detachment-induced cell death)." (PMID 33718218, 2021). "ILK, an ankyrin, repeat-containing serine/threonine protein kinase, plays a significant role in biological processes associated with tumorigenesis, including cancer cell proliferation, angiogenesis, metastasis, and drug resistance." (PMID 32117786, 2019).
cancer (continued). "ILK has been implicated in cancer cell growth and survival by modulating AKT signaling." (PMID 28845464, 2017). "Since aberrant proliferation is a hallmark of early cancer, ILK may play an important role in maintaining homeostasis and limiting early cancer." (PMID 25669897, 2015). "In this study, we report a regulatory feedback loop between HIF-1α and integrin-linked kinase (ILK) that might underlie the ability of cancer cells to maintain high levels of HIF-1α expression and to promote EMT under hypoxic conditions." (PMID 25821081, 2015). "Previous studies have demonstrated that inhibition of ILK may be an underlying approach for treating cancer." (PMID 25760437, 2015). "The phenotypic changes and increased sensitivity to DZ-50 observed in DU-145 cells with low talin expression, and PC-3 cells harboring loss of ILK function, support a regulatory role for these two critical components of the focal adhesion complex in cancer cell anoikis resistance." (PMID 24497940, 2014). "Integrin-linked kinase (ILK) is a serine-threonine kinase that transduces extracellular matrix-related cues into intracellular signals, with fundamental roles in cell motility, development and cancer." (PMID 24024606, 2013). "Integrin-Linked Kinase (ILK) has been postulated as potent druggable cancer target." (PMID 19649326, 2009). "Similarly, the overexpression of ILK signaling has been observed to play an important role in biological processes associated with tumorigenesis, including the cell proliferation and growth of cancer cells." (PMID 37834385, 2023). "Increased protein levels and activity of ILK have been associated with the oncogenesis and tumour progression of many types of malignancies (the prostate, ovary, breast, colon, pancreas, stomach, and liver), indicating that ILK represents a potential target for new cancer treatments." (PMID 30276218, 2018). "In contemporary research, upregulation of ILK expression occurs in many human malignant tumors and has a strong correlation with poor prognosis, thus ILK has been more studied in tumor diagnosis and prognosis." (PMID 40171447, 2025). "CA, a hallmark of aggressive cancers, involves TACC3 forming a complex with integrin-linked kinase and chTOG at the centrosomes of CA cancer cells." (PMID 39603208, 2025). "We elucidate a novel mechanism whereby CPLF orchestrates myofibroblast–cancer cell crosstalk via the FN1/ILK/FAK pathway to drive tumour progression." (PMID 41405822, 2025). "ILK has been determined as the target of miR-542-3p and miR-625-3p in different pathologies, especially cancer." (PMID 38734696, 2024). "Serrano and colleagues reported that the KO of integrin-linked kinase (ILK), a kinase associated with cancer progression, induces upregulation of sGCβ1 in VSMCs, accompanied by an increase in the enzymatic activity of sGC." (PMID 39337539, 2024). "Significant canonical pathways included Molecular Mechanisms of Cancer, ILK Signaling, Integrin Signaling, RAC Signaling, and TREM1 Signaling." (PMID 38297314, 2024). "Several investigations have identified ILK as a biomarker, especially in cancer since its involvement in migration and invasion processes." (PMID 38734696, 2024). "The transmembrane protein CCDC25 functions as a receptor for NETs-DNA on the surface of cancer cells, activating the ILK/β-parvin/RAC1 pathway and enhancing cancer cell motility by sensing extracellular NETs-DNA." (PMID 38664728, 2024). "L1CAM is a known mediator of VCO in pericytes that reinforces de β1-integrin/ILK signaling pathway but it also mediates the spread of cancer cells into the vasculature and the interaction between cancer cells." (PMID 38255995, 2024).
cancer (continued). "On the other hand, a non-canonical activation of Notch 1 can be induced by other signaling pathways in many cancer cells and activation of ILK was reported to be upstream of Notch 1 pathway in leukemic cells." (PMID 39430758, 2024). "Integrin-linked kinase (ILK) is a widely expressed and highly conserved serine/threonine protein kinase associated with cancer progression." (PMID 39050887, 2024). "While under homeostasis ILK activation is transient as a biological switch for many signal transduction pathways, in pathological conditions (e.g. cancers) ILK is constitutively activated." (PMID 38077324, 2023). "ILK is found at the centrosome of a variety of cancer cells where it regulates several pathways related to division and mitotic spindle formation." (PMID 37508338, 2023). "During division, cancer cells with supernumerary centrosomes are significantly more sensitive to anti-ILK drugs than normal cells with two centrosomes." (PMID 37508338, 2023). "Despite considerable evidence linking ILK to cancer, a mechanistic understanding of the role for ILK in cancer progression is yet to be fully realized." (PMID 38077324, 2023). "Our study further emphasises the critical involvement of myeloid cell biology in cancer progression and we demonstrate that ILK is required for macrophage M2 polarization." (PMID 38077324, 2023). "ILK localizes to the centrosome of cancer cells and we have shown that ILK immunoreactivity was significantly inhibited by ILK siRNA treatment." (PMID 37508338, 2023). "Given that this and other proteins at the centrosome are also targetable for cancer, future studies will need to explore how these proteins interact with ILK and ABL to regulate centrosome function and mitoses in cancer cells." (PMID 37508338, 2023). "Comprehensive analysis of the altered phosphoproteins using ROMA software revealed up-regulation of several cancer hallmark pathways such as MAPK, mTOR and integrin/ILK/actin, affecting epithelial and stromal colonic cells." (PMID 37696912, 2023). "The multifunctional proteins integrin-linked kinase (ILK) and Abelson kinase (ABL) are established therapeutic targets for many different cancers with elevated expression of these oncogenic proteins." (PMID 37508338, 2023). "Integrin-linked kinase (ILK), a multifunctional, scaffolding, pseudo-kinase regulating many integrin-mediated cellular processes, is highly expressed in many cancers." (PMID 38077324, 2023). "The centrosome serves as a scaffold for many signalling proteins in cancer cells including ILK and ABL." (PMID 37508338, 2023). "For examples, our earlier report demonstrates a correlation between ILK overexpression and markers of M2 macrophages, indicating a cancer-promoting cue driving ILK upregulation." (PMID 38077324, 2023). "The TACC3-ch-TOG complex clusters supernumerary centrosomes in cancer cells in an ILK-and Aurora-A-dependent manner." (PMID 37508338, 2023). "ILK exists as a tubulin-based multiprotein complex at centrosomes where it acts to cluster supernumerary centrosomes found in cancer cells." (PMID 37508338, 2023). "ILK overexpression is a feature in the progression of many cancers such as colon, gastric, prostate, breast, melanoma as well as leukaemia." (PMID 38077324, 2023). "Elevated ILK expression has been detected in various human cancers originating from epithelial cells." (PMID 36768775, 2023). "Regardless of the mechanism, several recent studies have shown that ILK downregulation or inhibition sensitizes cancer cells to various chemotherapeutics that target ABL or BCR-ABL." (PMID 37508338, 2023). "Noteworthy, there is a strong correlation between elevated ILK expression and enhanced differentiation in normal gastrointestinal, neural, bone marrow, renal tissue, and more differentiated areas of malignant tumors." (PMID 35089438, 2022).
cancer (continued). "We found that there was a pronounced correlation of ILK expression with most of common immune checkpoints ligands in COAD compared with the other cancers." (PMID 35692780, 2022). "The results showed that ILK expression is upregulated in advanced Duke’s stages B to D compared with stage A, suggesting a role in cancer invasion and metastasis." (PMID 35692780, 2022). "Several mitotic kinases, namely, PLK1, Aurora kinases, Rho-associated protein kinase 1, and integrin-linked kinase, are considered in this review, as an understanding of the shared machineries between mitosis and metastasis could be helpful for developing new strategies to treat cancer." (PMID 35379935, 2022). "The expression of ILK in different cancers compared with their adjacent normal tissues from the TCGA was determined using the TIMER database." (PMID 35692780, 2022). "In CRC, overexpression of ILK is associated with genomic instability, epithelial-mesenchymal transition (EMT), and cancer stem cells (CSCs) traits, which contribute to tumor progression, migration, invasion, and chemoresistance via NF-κB, CTEN signals, etc.." (PMID 35427373, 2022). "We have previously found that α-Catulin interacted with ILK, induced ILK activation, and produced a positive signaling feedback loop that contributed to cancer metastasis." (PMID 35154481, 2022). "Recent studies have demonstrated that the expression of ILK modulates the resistance of cancer cells to therapeutic initiatives." (PMID 35804980, 2022). "In summary, these results indicate that the ILK inhibitor OSU-T315 effectively targeted α-Catulin-mediated cancer stemness in NSCLC." (PMID 35154481, 2022). "Overall, ILK mRNA expression is higher in certain cancers compared with normal tissues in 37 datasets, whereas its expression is lower in other cancers compared with normal tissues in 70 datasets." (PMID 35692780, 2022). "Abnormal expression of ILK has been reported in diverse cancers, and it has been used as a biomarker for cancer diagnosis and prognostication." (PMID 35379935, 2022). "ILK, bound to the cytoplasmic tails of integrin β1, β2, and β3, was known to play an important role in cancer development and therapy." (PMID 35379775, 2022). "Studies in colonization-competent cancer cells have demonstrated the importance of an ILK/β-parvin/cofilin signaling axis in regulating FLP stability." (PMID 35804980, 2022). "It is becoming increasingly clear that ILK is a vital negative regulator of the Hippo tumor suppressor pathway in cancer cells." (PMID 35804980, 2022). "It has been established previously that ILK is upregulated in different cancers compared to normal tissues." (PMID 35692780, 2022). "In particular, ILK’s role in tumor progression has been solidified and ILK is considered to be a validated target for cancer therapy." (PMID 35804980, 2022). "Cancer patients had strikingly higher ILK levels in serum compared to a barely detectable level in healthy volunteers." (PMID 35089438, 2022). "It has been demonstrated that the transcription of SNAIL1 can be regulated by ILK protein in certain cancers." (PMID 35379775, 2022). "A particularly interesting aspect of ILK signaling is its function as a major component of a central pathway that enables colonization by disseminated cancer cells (DCCs) immediately subsequent to extravasation and during exit from latency or dormancy." (PMID 35804980, 2022). "ILK is widely overexpressed in different cancers and its upregulation is closely related to tumor grade and survival." (PMID 35676936, 2022). "Although it has been demonstrated that the transcription of SNAIL1 can be regulated by ILK protein in certain cancers." (PMID 35379775, 2022). "Recent work has uncovered a unique role of ILK signaling in cross-talk between cancer cells and adjacent normal cells mediated by small extracellular vesicles (sEV)." (PMID 35804980, 2022).
cancer (continued). "In contrast the normal tissues from non-cancer individuals exhibit low expression of ILK and the other genes." (PMID 35692780, 2022). "ILK expression or activity was often elevated in various human cancers, such as stomach, pancreas, colon, and malignant melanoma." (PMID 35778385, 2022). "ILK was recently discovered to be overexpressed in several cancers (the prostate, ovary, breast, colon, lung, and thyroid), contributing to their proliferation, invasion, and metastasis by regulating EMT-related genes." (PMID 35481240, 2022). "To investigate this further we examined the expression level of ILK mRNA from different datasets in different cancers compared with normal tissues using the Oncomine platform." (PMID 35692780, 2022). "Studies in SOC further illustrate the link between increased levels of ILK and ILK-mediated negative regulation of the Hippo pathway in cancer cells to promote EMT." (PMID 35804980, 2022). "Inhibition of this signaling axis reduces cancer cell proliferation in vitro and suppresses lung metastasis in vivo, demonstrating the importance of this ILK-mediated signaling cascade in controlling metastatic propensity." (PMID 35804980, 2022). "The ILK/AKT and mTOR signaling pathway regulates various aspects of cell development and is also implicated in the progression of human carcinomas." (PMID 35676936, 2022). "The ILK pathway has been associated with migration, invasion, EMT, cancer stem cell marker and chemotherapy resistance in CRC." (PMID 34233735, 2021). "ILK is a critical regulator of the cancer-survival pathway, including PI3K/AKT, glycogen synthase kinase 3β (GSK3β), nuclear factor-kappaβ (NF-κβ), mTOR, or Snail1/E-cadherin/N-cadherin." (PMID 33916175, 2021). "The present study adds ILK as an essential component in the molecular mechanisms driving cancer cell invasion, making it a potential marker for pre-symptomatic cancers and exploitable as a therapeutic target in those cancers." (PMID 33671549, 2021). "NET DNA binds to CCDC25 and induces an integrin linked kinase (ILK)-β-PARVIN-RAC1-CDC42 cascade, resulting in the metastasis of cancer cells." (PMID 34758877, 2021). "More importantly, although there is less understanding of the role for ILK in cellular senescence in the cancer context, some reports that have suggested an involvement for ILK in cellular senescence regulation." (PMID 34163519, 2021). "In cancer, ILK and adaptor proteins regulate interactions between tumor cells and the extracellular environment to activate signaling pathways that promote cell proliferation, migration, and epithelial-to-mesenchymal transition." (PMID 34373451, 2021). "This review summarizes up-to-date studies of ILK and its crosstalks with signaling pathways involved in cancer growth and progression." (PMID 34163519, 2021). "Centrosome clustering is regulated by ILK in cancer cells and this is an important process for cell survival." (PMID 34163519, 2021). "ILK has significant effects on the development and progression of human carcinoma 20, 43, 44, including promoting the metastatic behaviour of EOC cells." (PMID 33531984, 2021). "A significant enrichment of the ILK pathway was identified in 22 of the 24 cancer specimens, identifying this pathway as a potential player in the transformation of normal ovarian cells to cancerous cells." (PMID 33256002, 2020). "Recently, evidences suggested that, ILK was overexpressed in many cancers and contributed to proliferation, invasion and metastasis 11-13." (PMID 31897228, 2020). "ILK plays a vital role in cancer research and facilitates various cellular functions such as survival, cytoskeletal dynamics, and proliferation." (PMID 31938742, 2020). "Upregulation of ILK is frequently observed in cancer tissues compared to corresponding normal tissues." (PMID 33256002, 2020). "In fact, increased ILK expression has been correlated with cancer progression in several cancer types, rendering ILK a potential anti-cancer therapeutic target." (PMID 33043811, 2020).